RN7SKP222 (RN7SK pseudogene 222)
Gene: Miscellaneous RNA gene on chromosome 3 (192,093,122 to 192,093,436, forward strand). Ensembl gene ENSG00000222583.
Homologues: Orthologues: chimpanzee 7SK (88% identical). Paralogues in human: RN7SKP124 (74% identical), 7SK (73% identical), RN7SKP44 (72% identical), RN7SKP9 (72% identical), RN7SKP150 (71% identical), RN7SKP176 (71% identical), RN7SKP47 (71% identical), RN7SKP78 (71% identical), RN7SKP187 (71% identical), RN7SKP189 (71% identical), RN7SKP269 (71% identical), RN7SKP115 (70% identical), and 284 more.